STAT4 (signal transducer and activator of transcription 4)
Diseases named in the same sentence as STAT4 in open-access papers (continued):
Sharing a sentence is not in itself a finding about the gene and the disease.
demyelination (1 paper, 2011). "To assess the possible involvement of host IL-2 in the HSV-IL-2-induced demyelination, we used BALB/c-STAT4−/− mice, which do not mount a TH1 response, and BALB/c-STAT6−/− mice, which do not mount a TH2 response." (PMID 21364747, 2011).
endotoxemia (1 paper, 2024). "Mice lacking STAT4 are highly susceptible to lethal endotoxemia." (PMID 38673659, 2024).
enthesitis-related arthritis (1 paper, 2015). "As with the STAT4 rs7574865 G/T polymorphisms, presence of hepatomegaly and enthesitis-related arthritis had strong effect on the association." (PMID 25781893, 2015).
gastroenteritis (1 paper, 2022). An inflammatory disorder that affects the upper and lower gastrointestinal tract. "Activation of this chemokine pathway further promotes an acute immune response and inflammation via the Stat proteins; Stat1 and Stat3 in case of the patients with retinitis and Stat4 in case of the patients with gastroenteritis which aggravates the severity of the disease." (PMID 35538132, 2022).
gliosarcoma (1 paper, 2018). A rare histological variant of glioblastoma (WHO grade IV) characterized by a biphasic tissue pattern with alternating areas displaying glial and mesenchymal differentiation (WHO). "STAT4 is phosphorylated by JAK2, and we confirmed that the JAK2-inhibitor ruxolitinib was more cytotoxic at comparable micromolar concentrations than TMZ in two gliosarcoma cultures, meriting further exploration in preclinical models." (PMID 29416795, 2018).
Glucose intolerance (1 paper, 2017). Glucose intolerance (GI) can be defined as dysglycemia that comprises both prediabetes and diabetes. "BMC that expressed STAT4 induced increases in glucose intolerance and IR compared to STAT4-deficient cells." (PMID 28400678, 2017).
HIV-1 infection (1 paper, 2025). The type species of lentivirus and the etiologic agent of acquired immunodeficiency syndrome (AIDS). "Both processes may exacerbate chronic inflammation and immune dysregulation in HIV-1 infection, underscoring the multifaceted nature of STAT4’s potential involvement in HIV pathogenesis." (PMID 41009690, 2025).
Hyperglycemia (1 paper, 2022). An increased concentration of glucose in the blood. "The TR-hnRNPA2B1 complex has been reported to repress proliferation, migration, and tube formation of HRECs in hyperglycemia through the STAT-4/miR-223-3p/FBXW7 signaling pathway." (PMID 35308095, 2022).
hyperthyroidism (1 paper, 2021). Overactivity of the thyroid gland resulting in overproduction of thyroid hormone and increased metabolic rate. "STAT4 knockout aggravated the immune abnormalities and hyperthyroidism of GD mice and accelerated the progress of GD,31, 32 which is consistent with our findings and indicated that STAT4 could promote the function and differentiation of Treg cells." (PMID 34431214, 2021).
immune deficiencies (1 paper, 2024). "Numerous genes have been implicated in the pathogenesis of SLE, particularly components of the interferon pathways such as IRF5, STAT4, and SPP1, which likely reflect intrinsic immune deficiencies in SLE patients." (PMID 39194726, 2024).
inclusion body myositis (1 paper, 2023). A slowly progressive degenerative inflammatory disorder of skeletal muscles characterized by late onset weakness of specific muscles and distinctive histopathological features. "We identified more significant associations than those previously reported in IIM for STAT4 and DGKQ in the total cohort, for NAB1 and FAM167A‐BLK loci in PM, and for CCR5 in inclusion body myositis." (PMID 36580032, 2023).
ischemic heart disease (1 paper, 2021). "STAT1 and STAT3 have been shown to play roles in ischemic heart disease, and in our study, we found that a gene in the STAT family (STAT4) was a human-specific DEG." (PMID 34003819, 2021).
leukopenia (1 paper, 2019). "Patients carrying the STAT4 rs7574965 variant allele had a higher risk of monoclonal component and leukopenia (P = 0.002, OR = 7.6; P = 0.048, OR = 2.01, respectively)." (PMID 30882006, 2019).
male infertility (1 paper, 2022). The inability of the male to effect fertilization of an ovum after a specified period of unprotected intercourse. "In addition, members of the JAK-STAT pathway, TYK2, STAT1 and STAT4, have been shown to be active in human sperm, indicating that defects in the JAK-STAT pathway in sperm may be related to male infertility." (PMID 36003498, 2022).
metastatic cancer (1 paper, 2019). A carcinoma which has spread from the original site of growth to another anatomic site. "However, given that serum IL-12 levels are significantly lower in metastatic cancer patients compared to non-metastatic patients, it is possible that the diminished IL-12 production potentially contributes to the increased metastasis observed in tumor bearing Stat4−/− mice." (PMID 32010142, 2019).
methicillin-resistant Staphylococcus aureus (1 paper, 2021). "In this report, we demonstrate that STAT4-deficient mice were acutely sensitive to methicillin-resistant Staphylococcus aureus (MRSA) infection." (PMID 34138758, 2021).
migraine (1 paper, 2021). "A recent biocomputational genetic association analysis of migraine and RA demonstrated that there is a phylogenetic relationship between the genes responsible for migraine and RA, such as SLC24A3 and HLA-B, MPPED2 and STAT4, and ATP1A2 and IL6R, respectively." (PMID 35281991, 2021).
myositis (1 paper, 2018). "A large scale immunochip study has shown that PTPN22, UBE2L3, CD28, TRAF6, and STAT4 are associated with myositis of Caucasian descents: PTPN22 was primarily associated with PM." (PMID 29854780, 2018). "STAT4 had been shown to associate with myositis in a Japanese population." (PMID 29854780, 2018).
ocular infection (1 paper, 2010). "In contrast to vaccinated STAT4−/− mice, mock-vaccinated STAT4−/− mice had higher ocular HSV-1 titers than mock-vaccinated BALB/c mice on days 2–3 post-ocular infection." (PMID 20104254, 2010). "All of the vaccinated STAT4−/− and BALB/c mice survived lethal ocular infection." (PMID 20104254, 2010). "Thus, even in the absence of STAT4, vaccination protected 100% of the mice against lethal ocular infection." (PMID 20104254, 2010).
optic neuritis (1 paper, 2023). Optic neuritis is inflammation of the optic nerve, the nerve that carries the visual signal from the eye to the brain.The conditionmay cause sudden, reduced vision in the affected eye(s). "The aim of the study was to evaluate the associations of STAT4 (rs10181656, rs7574865, rs7601754, rs10168266) gene polymorphisms and STAT4 serum level in patients with optic neuritis." (PMID 38202017, 2023). "Therefore, the aim of this study is to determine the associations of STAT4 (rs10181656, rs7574865, rs7601754, rs10168266) with the manifestation of optic neuritis." (PMID 38202017, 2023). "The current findings may indicate a risk role of STAT4 (rs10181656, rs7574865, rs7601754, rs10168266) G-G-A-C and C-T-A-T haplotypes in the occurrence of optic neuritis." (PMID 38202017, 2023). "In optic neuritis without MS occurrence, STAT4 (rs10181656, rs7574865, rs7601754, rs10168266) haplotypes G-G-A-C and C-T-A-T were found to be associated with 32.6- and 9-fold increased odds of ON without MS (p = 0.002, p = 0.016, respectively)." (PMID 38202017, 2023). "Moreover, when considering cases of optic neuritis without MS, the same STAT4 haplotypes, G-G-A-C and C-T-A-T, demonstrate notable associations with 32.6- and 9-fold increased odds, supported by p-values of 0.002 and 0.016, respectively." (PMID 38202017, 2023).
osteosarcoma (1 paper, 2014). A usually aggressive malignant bone-forming mesenchymal neoplasm, predominantly affecting adolescents and young adults.
paracoccidioidomycosis (1 paper, 2025). A systemic fungal infection caused by Paracoccidioides brasiliensis that is most often seen in immunocompromised patients. "It appears that an autosomal dominant STAT4 LOF leads to impaired IL-12-dependent IFN-γ immunity, resulting in an increased risk of paracoccidioidomycosis." (PMID 41164159, 2025). "In a case report of a Brazilian patient who is heterozygous for STAT4 LOF, the patient presented with paracoccidioidomycosis." (PMID 41164159, 2025).
Parkinson disease (1 paper, 2025). A progressive degenerative disorder of the central nervous system characterized by loss of dopamine producing neurons in the substantia nigra and the presence of Lewy bodies in the substantia nigra and locus coeruleus. "The research showed that STAT4 regulated the transcription of KISS1 to inhibit the oxidative damage, inflammation and neuronal apoptosis in the model of Parkinson’s disease." (PMID 40214477, 2025).
penile cancer (1 paper, 2024). A primary or metastatic malignant neoplasm that affects the penis. "In summary, our findings revealed that the complexity of JAK-STAT-SOCS1 axis and the predominant role of STAT4 in penile cancer, which can mediate tumorigenesis, malignant progression, and lymphatic metastasis." (PMID 38774752, 2024). "STAT4 was an important dominant molecule in penile cancer, which mediated the immunosuppressive tumor microenvironment by driving the apoptosis of cytotoxic T cell and was also a valuable biomarker of immune checkpoint inhibitor treatment response." (PMID 38774752, 2024). "In order to make a comprehensive investigation to reveal the mechanism of STAT4 in penile cancer, molecular interaction analysis of STAT4 were applied to reveal its important accessory molecules in our study." (PMID 38774752, 2024). "As we discovered in our current study, STAT4 appeared to be a protagonist in mediating tumorigenesis, malignant progression and lymphatic metastasis of penile cancer." (PMID 38774752, 2024). "We speculated that the overexpression of STAT4 contributed to make the formation of an immunosuppressive microenvironment in penile cancer and further promote the malignant progression." (PMID 38774752, 2024). "Therefore, it was reasonable to infer that the STAT4 was an essential biomarker of penile cancer." (PMID 38774752, 2024). "There was a noticeable difference in the expression of JAK3, STAT4 and STAT5A between primary penile cancer and their metastatic lymph nodes." (PMID 38774752, 2024). "During lymph node metastasis phase of penile cancer, the expression evolution of JAK-STAT-SOCS1 axis was characterized by the upregulation of JAK3, STAT4 and STAT5B." (PMID 38774752, 2024). "During malignant progression phase of penile cancer, the expression evolution of JAK-STAT-SOCS1 axis was characterized by the upregulation of JAK1, JAK3, STAT4, STAT5A and STAT6." (PMID 38774752, 2024). "During tumorigenesis phase of penile cancer, the expression evolution of JAK-STAT-SOCS1 axis was characterized by the upregulation of JAK2, STAT1, STAT2, STAT3 and STAT4." (PMID 38774752, 2024). "We further hypothesized that STAT4 overexpression may enhance the expression of PD-1 or CTLA4, which suggested its potential as an important predictive biomarker for immunotherapy response in penile cancer patients." (PMID 38774752, 2024).
pericarditis (1 paper, 2014). An inflammatory process affecting the pericardium. "STAT4, that showed the strongest association with the disease, was also associated with a higher risk to develop pericarditis, while HCP5 SNPs resulted associated with anti-Ro/SSA, anti-dsDNA and aCL." (PMID 25369137, 2014). "The genotype/phenotype correlation analysis showed several associations including a higher risk to develop pericarditis with STAT4, and an association between HCP5 rs3099844 and anti-Ro/SSA antibodies." (PMID 25369137, 2014).
periodontitis (1 paper, 2021). An acute or chronic inflammatory process that affects the tissues that surround and support the teeth. "Thus, evidence suggests STAT5B and STAT4 may mediate immunosuppression during periodontitis." (PMID 33777111, 2021). "Of the top 10 hub TFs, six “leader” immunosuppressive TF-target DEGs with plausible literature evidence were identified as key to periodontitis pathogenesis and included the down-regulated TFs (NFKB1, FOS, and JUN), as well as up-regulated TFs (HIF1A, STAT5B, and STAT4)." (PMID 33777111, 2021).
pituitary adenomas (1 paper, 2024). "The STAT4 rs10181656, rs7574865, rs7601754, and rs10168266 single nucleotide polymorphisms were analyzed to evaluate the associations with the pituitary adenoma size." (PMID 39597056, 2024). "Genotype frequencies, allele distributions, and serum STAT4 levels were statistically analyzed to assess associations with pituitary adenoma occurrence." (PMID 39597056, 2024). "STAT4 rs10181656, rs7574865, rs7601754, and rs10168266 were analyzed to evaluate the associations with the pituitary adenoma size." (PMID 39597056, 2024). "Our study observed elevated STAT4 serum levels in patients with pituitary adenomas (PAs) compared to the reference group, suggesting a potential role for STAT4 in PA pathogenesis." (PMID 39597056, 2024). "Background/Objectives: This study aims to investigate whether Signal Transducer and Activator of Transcription 4 (STAT4) influences the anti-tumor immune response and is possibly involved in the initiation or relapse of pituitary adenomas (PAs) by examining STAT4 polymorphisms and serum levels." (PMID 39597056, 2024).
pneumocystis pneumonia (1 paper, 2018). "CD4+ T cells and STAT4/6, at least in a mouse model of pneumocystis pneumonia, are necessary for M2 macrophage MMP12 expression and RELM-α and CCL17 production." (PMID 29304863, 2018).
polyarthritis (1 paper, 2020). "Previous candidate gene association studies have shown that polyarthritis RF-positive JIA is associated with adult RA-associated loci, i.e., rs10499194 (TNFAIP3), rs2476601 (PTPN22), and rs7574865 (STAT4)." (PMID 33076506, 2020).
psoriatic arthritis (1 paper, 2023). Joint inflammation associated with psoriasis. "In 2016, Greek researchers published a study that found that the GG genotype and the G allele of STAT4 rs10181656 were significantly associated with the occurrence of psoriatic arthritis." (PMID 38275379, 2023).
pulmonary emphysema (1 paper, 2024). A subcategory of chronic obstructive pulmonary disease (COPD). "The increase of CD4+, CD8+ cells expressing NF-κB, STAT4, IFN-γ and perforin are related to smoking habit, smoking history, airflow rate, obstruction and pulmonary emphysema." (PMID 38903812, 2024).
rectum adenocarcinoma (1 paper, 2022). An adenocarcinoma arising from the rectum. "STAT4 was significantly upregulated in ESCA, HNSC, KIRC, KIRP, STAD, and THCA but significantly downregulated in BRCA, COAD, KICH, LUSC, and rectum adenocarcinoma (READ)." (PMID 36176415, 2022).
relapsing-remitting MS (1 paper, 2019). "With this study, we investigated the IL-12/STAT4, IL-23/STAT3, and IL-6/STAT3 pathways in patients with relapsing-remitting MS (RRMS) and the potential impact of genetic background on activation of these pathways." (PMID 30917537, 2019).
sarcoma (1 paper, 2019). A usually aggressive malignant neoplasm of the soft tissue or bone. "Gene set variation analysis (GSVA) performed on differentially expressed genes for each cluster showed the enrichment of IFNγ signaling and IL-12 signaling mediated by STAT4 in clusters enriched in Csf3r+/+ sarcomas (clusters 2 and 4), in line with data obtained by flow cytometry." (PMID 31257026, 2019).
sarcopenia (1 paper, 2020). Progressive decline in muscle mass due to aging which results in decreased functional capacity of muscles. "From the psoas muscle Hi-C dataset we identified unique druggable eGenes (e.g., GRID1, TNFRSF1A, STAT4) which represent potential therapeutic targets for treating the muscle wasting/weakness symptoms associated with NMD and sarcopenia." (PMID 32391060, 2020).
T-cell lymphomas (1 paper, 2023). "To reveal whether STAT4 downregulation in mature T-cell neoplasms is a phenomenon specific to T-PLL, we re-analyzed published gene expression profiling (GEP) array data from different entities of mature T-cell lymphomas (TCL) compared to either pooled CD4+ or CD8+ T cells." (PMID 37173993, 2023).
trachoma (1 paper, 2017). "STAT1 and STAT4 have previously been shown to be associated with active trachoma and ocular C. trachomatis infection, and STAT1 was upregulated in cervical epithelial cells infected with C. trachomatis in vitro which was found to inhibit chlamydial growth." (PMID 28966918, 2017).
viral hepatitis (1 paper, 2017). An acute or chronic inflammation of the liver parenchyma caused by viruses. "Functional dichotomy of NK cells in viral hepatitis was caused by two different signaling, phosphorylated STAT1 (pSTAT1) related to cytotoxicity and phosphorylated STAT4 (pSTAT4) related to cytokine production." (PMID 28328926, 2017).
visceral leishmaniasis (1 paper, 2010). A severe form of leishmaniasis characterized by irregular bouts of fever, substantial weight loss, swelling of the spleen and liver, and anemia (which may be serious). "The IL-18-independent effect of IL-12 on NK-cell activation in visceral leishmaniasis might result from an increased nuclear translocation of STAT4 and/or NF-κB as previously seen in NK cells present in unseparated mouse macrophage populations 36,37." (PMID 20213736, 2010).